CASP5 (caspase 5)
Diseases named in the same sentence as CASP5 in open-access papers (continued):
Sharing a sentence is not in itself a finding about the gene and the disease.
kidney cancer (2 papers, 2009 to 2022). Primary or metastatic malignant neoplasm involving the kidney. "Patients harboring this specific haplotype show higher risk of RCC development, also identifying specific CASP1 and CASP5 variants associated with enhanced kidney cancer risk." (PMID 35682876, 2022). "Enhanced expression of AIM2, caspase-5, NOD2, and FOXD2-AS1 pyroptosis regulators in ccRCC are associated with a poor kidney cancer prognosis." (PMID 35682876, 2022). "We had the opportunity to conduct a quick replication of our most statistically significant finding, CASP5 SNP rs507879 in the US Kidney Cancer Study population." (PMID 19603096, 2009). "Also, caspase-5, a non-canonical inflammasome pyroptosis protein member, involves innate immunity in kidney cancer evolution and progression, as well as GZMB, which is used by cytotoxic lymphocytes as protection against malignant cells." (PMID 35682876, 2022).
neutropenia (2 papers, 2023 to 2025). A decrease in the number of neutrophils found in the blood. "Some polymorphisms, including TLR4 and CASP5, have been associated with a decreased probability of developing neutropenia." (PMID 40227705, 2025). "Whilst the link between the CASP5 rs554344 SNP WT allele and decreased probability of neutropenia may be explained by the key role of caspase-5 in the inflammasome (for review see Ref." (PMID 37162533, 2023).
preeclampsia (2 papers, 2023 to 2024). Preeclampsia is a hypertensive disorder of pregnancy that is characterized by new-onset hypertension with proteinuria presenting after 20 weeks of gestation, and depending on mild or severe forms may initially present with severe headache, visual disturbances, and hyperreflexia. "Likewise, we also recently observed that not only caspase 8 but also caspase 5 were enhanced in the placental tissue of women with late-onset preeclampsia." (PMID 38791563, 2024).
prostate carcinoma (2 papers, 2022 to 2023). A carcinoma that arises from epithelial cells of the prostate gland. "A retrospective study showed that mRNA expression of Caspase-5 was significantly elevated in patients with prostate cancer, indicating that Caspase-5-involved pyroptosis may be related to the risk of PCa." (PMID 36702978, 2023).
ankylosing spondylitis (1 paper, 2018). An autoimmune chronic inflammatory disorder characterized by inflammation in the vertebral joints of the spine and sacroiliac joints. "In addition, caspase-5 was shown to be upregulated in peripheral blood of fibromyalgia patients reporting high pain, in contrast to those with low pain and in patients with ankylosing spondylitis." (PMID 28361271, 2018).
cataract (1 paper, 2024). Partial or complete opacity of the crystalline lens of one or both eyes that decreases visual acuity and eventually results in blindness. "The delayed onset of signs of premature aging compared to Werner syndrome (e.g., cataracts in their 40s in CASP5 homozygotes vs cataracts in their 30s in classical Werner patients) is consistent with the mild but significant increase of inflammatory cytokines." (PMID 37603195, 2024).
familial Mediterranean fever (1 paper, 2025). Familial Mediterranean fever (FMF) is an autoinflammatory disorder characterized by recurrent short episodes of fever and serositis resulting in pain in the abdomen, chest, joints and muscles. "These factors were IL-1β, prostaglandin-endoperoxide synthase 2 (PTGS2/COX-2), NOD-like receptor family CARD domain-containing protein 4 (NLRC4), Familial Mediterranean Fever (MEFV) gene, and caspase 5 (CASP5)." (PMID 40861543, 2025).
gastric tumors (1 paper, 2023). "Our results confirmed that the expression of GPX4, CASP6, IL-6, CASP5, CASP4, and TIRAP was greatly up-regulated in gastric tumors relative to normal tissues." (PMID 37595258, 2023).
gram-negative bacterial infections (1 paper, 2021). Infections caused by bacteria that show up as pink (negative) when treated by the gram-staining method. "While non-classical pathways are mainly mediated by human homologous genes caspase-4, caspase-5 or mouse caspase-11, which can be activated by various Gram-negative bacterial infections." (PMID 34484243, 2021).
inflammatory bowel disease (1 paper, 2023). A spectrum of small and large bowel inflammatory diseases of unknown etiology. "In conclusion, we systematically summarized the landscape of pyroptosis in inflammatory bowel disease and identified AIM2, CASP1, CASP5, GSDMD, and NLRP3 as hub genes." (PMID 37740137, 2023).
iron deficiency (1 paper, 2021). "Furthermore, iron deficiency has been shown to inhibit expression not only of CTSZ, the gene for the cysteine protease cathepsin Z, which has been associated with malignancy and inflammation, but also of CASP5, the gene for the cysteine peptide Caspase 5, which is involved in cellular apoptosis." (PMID 33777027, 2021).
liver cirrhosis (1 paper, 2023). "To understand if differential regulation of CASP4 versus CASP5 was specific to Gram-negative sepsis or general to severe infections with immunosuppression, we studied a cohort of patients with liver cirrhosis and acute decompensation and ascites." (PMID 38106412, 2023).
lung squamous cell carcinoma (1 paper, 2020). "Interestingly, the Serine conserved position that corresponds to the Ser-384 residue in caspase-2 is also subjected to missense mutagenesis in caspase-5 and -6 in lung squamous cell carcinoma and adenocarcinoma." (PMID 33011746, 2020).
lupus (1 paper, 2024). "In this study, we confirmed the enhanced Caspase 5/11‐induced GSDMD activation in macrophages of lupus patients and lupus‐prone MRL/lpr mice." (PMID 38881675, 2024). "This study identified increased activation of both Caspase 1 and Caspase 5/11 in the PBMCs of SLE patients and in the kidneys of lupus mice, indicating the coexistence of both pyroptosis pathways in SLE." (PMID 38881675, 2024). "We observed increased Caspase 5/11 and GSDMD‐dependent pyroptosis in the macrophages/monocytes of both lupus patients and mice." (PMID 38881675, 2024).
malaria (1 paper, 2024). Malaria is a serious and sometimes fatal disease caused by a parasite that commonly infects a certain type of mosquito which feeds on humans. "Notably, complement genes (C1QA, C1QB, C1QC), apoptotic genes (PDL1, PDL2, APOL1, APOL2, FAS), inflammatory caspases (CASP1, CASP5), TLR pathway genes (TLR1, TLR4, TLR5, TLR8), cytokines (IL6, IL10), and granzyme (GZMB) were among the genes upregulated during symptomatic malaria." (PMID 39161730, 2024).
non-small cell lung carcinoma (1 paper, 2023). A group of at least three distinct histological types of lung cancer, including non-small cell squamous cell carcinoma, adenocarcinoma, and large cell carcinoma. "GSDMD, CASP1, CASP4 and CASP5 gene expression are highly increased in PBMCs of non-small cell lung cancer patients and their expression are closely related to the clinical characteristics of patients." (PMID 37194012, 2023).
Obesity (1 paper, 2020). Accumulation of substantial excess body fat. "Apart from regulating obesity‐associated inflammation, CASP5 might be particularly important for carcinogenesis." (PMID 32311223, 2020).
periodontitis (1 paper, 2022). An acute or chronic inflammatory process that affects the tissues that surround and support the teeth. "In this study, we demonstrated that circ_0138959 contributed to the dysfunction of HGFs by competing with CASP5 to bind with miR-527 in periodontitis in vitro." (PMID 35030963, 2022). "Our research suggested that circ_0138959 acted as a ceRNA to contribute to the dysfunction of HGFs via the miR-527/CASP5 axis in periodontitis in vitro." (PMID 35030963, 2022).
pneumonia (1 paper, 2023). An acute, acute and chronic, or chronic inflammation focally or diffusely affecting the lung parenchyma, caused by an infection in one or both of the lungs (by bacteria, viruses, fungi, or mycoplasma.). "We found that caspase-4 and caspase-5 mRNA levels significantly upregulated in the PBMCs of pneumonia patients with severe phenotype, while they slightly increased in non-severe patients compared to healthy controls, and increased in BALF of severe cases compared with the non-severe group." (PMID 37180156, 2023).
pregnancy diseases (1 paper, 2023). "An altered expression of caspase 8 in the placentas of women with different obstetric complications like preterm labor and PE has been reported in past works; although, to our best knowledge, the expression of caspase 5 in the placental tissue has not been evaluated in pregnancy diseases." (PMID 38002326, 2023).
squamous carcinoma (1 paper, 2020). "ROC analyses showed that the detection of caspase-4 in lung tumor masses was an excellent diagnostic tool for both adenocarcinoma (red line) and squamous carcinoma (red line) compared to caspase-5 (green line)." (PMID 33187551, 2020).
type 2 diabetes (1 paper, 2020). "In human monocytes, CASP5 and CASP4 could be activated by saturated fatty acids, then trigger IL‐1β and IL‐18 release, which contributed to type 2 diabetes." (PMID 32311223, 2020).
ulcerative colitis (1 paper, 2021). An inflammatory bowel disease involving the mucosal surface of the large intestine and rectum. "Pyroptosis, a highly inflammatory form of lytic programmed cell death, with initiation via activation of caspase family, including caspase-1, caspase-4, caspase-5, and caspase-11, can be triggered by various diseases, such as ulcerative colitis." (PMID 35008842, 2021).
tumor (37 papers, 2016 to 2025). "However, in this study, the administered product was monocyte-derived dendritic cells loaded with frameshift-derived neoantigens of TGFBR2 and caspase-5, in addition to tumor-associated peptide carcinoembryonic antigen (CEA)." (PMID 41463230, 2025). "Interestingly, TNFSF13B and CASP5 proved to be risk signature in TCGA cohort and correlated with advanced tumor stages in GSE53757." (PMID 32311223, 2020). "According to our results, CASP5 was firstly proved to be correlated with advanced tumor stages of ccRCC in GSE53757." (PMID 32311223, 2020). "This strategy could be extended beyond the model epitope S7Abu, as demonstrated by generation of XCL1-antigen conjugates with epitopes of tumor antigens gp100 (Y7A), TGFβRII (R7A) and caspase 5 (F7M)." (PMID 35428705, 2022). "Furthermore, TNFSF13B and CASP5 were proved to be correlated with advanced tumor stages in GSE53757." (PMID 32311223, 2020). "Regarding caspases, tumor cells exhibited predominantly high expression of CASP4, and immune cells showed high expression of CASP1, CASP4, and CASP8, while CASP5 plays an important role in stromal cells." (PMID 38229080, 2024). "Lymph node metastasis had significant difference with the CASP4 and GSDMD expression (P < 0.05); tumor volume had significant difference with CASP1 and CASP5 expression (P < 0.05)." (PMID 37194012, 2023). "We then constructed a nomogram for clinical prediction based on CASP3, CASP5, CASP8, GSDMC, age, and tumor status." (PMID 36882663, 2023). "According to our analytical results, CASP4, CASP5, and CASP9 were upregulated in the tumor tissues, and their high expression indicated poor survival rate." (PMID 35153782, 2022). "Three genes (ELANE, NLRP7, and CASP5) were downregulated, whereas seven others (GSDMC, IL1A, NOD2, GZMB, GSDMA, IL1B, and PLCG1) were overrepresented in the tumour group." (PMID 35087586, 2022). "To clarify the correlation between 7 PRGs (BTK, CASP5, EEF2K, GZMA, NR1H2, RIPK3, and SDHB) derived from LASSO Cox regression analysis and immune infiltration in COAD, we applied Tumor Immune Estimation Resource (TIMER) database on these genes." (PMID 35912258, 2022). "In the validation cohort from GSE53757, TNFSF13B, CASP5, and GJB6 correlated positively with tumor stages, while FREM1 negatively correlated with tumor stages." (PMID 32311223, 2020). "In these tumor tissue, most pyroptosis-related molecules, particularly IRF1, GZMB, CASP5, BAK1 and AIM2, were consistently inhibited in the cell cycle, DNA damage response, hormone AR and RTK signaling pathway, but highly activated in the apoptosis signaling way." (PMID 36437960, 2022). "In addition, tissue validation results also showed that CASP4, CASP5, PRKACA, and NOD1 were differentially expressed between tumor and normal tissues from COAD patients." (PMID 34938319, 2021). "A total of 24 pyroptosis-related genes shown significantly different expression between normal and tumor tissues in COAD and seven genes (CASP4, CASP5, CASP9, IL6, NOD1, PJVK, and PRKACA) screened by univariate and LASSO cox regression analysis were used to construct the risk model." (PMID 34938319, 2021). "Importantly, we further observed that TNFSF13B, CASP5 and XCR1 showed the remarkable correlations with tumor‐infiltrating immune cells." (PMID 32311223, 2020). "We analyzed the gene expression levels of 12 hub genes with clinical tumor stages and found that TNFSF13B, CASP5 and GJB6 correlated positively with tumor stages, while FREM1 showed negative associations with tumor stages." (PMID 32311223, 2020).
tumor (continued). "The up-regulation of cleaved-caspase-5 and caspase-7 provide further evidence of apoptosis, as do other findings that SEMA3A can sensitize tumor cells to curcumin, an anti-cancer agent that promotes apoptosis and poly ADP ribose polymerase (PARP) cleavage induced by SEMA3A." (PMID 26755661, 2016). "In addition, we also found that the genes (GSDM, IRF1, GZMB, and CASP5, etc.)with a higher frequency of CNV have higher expression differences between normal and tumour tissues and greater correlation with prognosis, which further highlights the key role of CNV in GC." (PMID 35923703, 2022). "Based on the verification of the tissues from COAD patients by the method of qPCR, the results showed that CASP4, CASP5, PRKACA, and NOD1 were expressed differentially between normal and tumor tissues." (PMID 34938319, 2021).
cancer (20 papers, 2015 to 2025). A tumor composed of atypical neoplastic, often pleomorphic cells that invade other tissues. "The rs3181320*C allele of CASP5 (exon 2), leading to an amino acid substitution, was suggested as a potential risk factor for cancer." (PMID 38785927, 2024). "However, one SNP was reported to be associated with rheumatoid arthritis, and mutations of CASP5 were detected in cancers." (PMID 38785927, 2024). "Methylation of GPX4, NLRP3, and CASP5 were associated with better prognosis in majority of cancers." (PMID 36605187, 2022). "Interestingly, CASP5 mutations are associated with cancers, while CASP1 and CASP4 mutations are not, suggesting a caspase‐5‐specific protective role against tumorigenesis that is in keeping with SASP‐driven senescence surveillance." (PMID 30916891, 2019). "Inflammatory caspases CASP4 and CASP5 were upregulated in both cell types, correlating with partial activation of inflammation pathways in myoblasts and a robust activation in cancer cells." (PMID 39009887, 2024). "As one of the main mediators of apoptosis, CASP5 was identified as a potential marker for the treatment of cancer." (PMID 35255915, 2022). "CHMP4C and CASP5 were hypomethylated in most cancer types, while PLCG1 and NLRP6 were hypermethylated in most cancer types." (PMID 35795676, 2022). "The four PRGs—CASP5, CASP8, IL6, and TIRAP—in this PPS were found to be closely associated with the development of cancers." (PMID 35255915, 2022). "AIM2 was differentially expressed in multiple cancers, including bladder, breast, esophageal, kidney, liver, lung, stomach, and endometrium, as well as CASP5, NOD2, and GZMB." (PMID 34906145, 2021). "Caspase-5 is involved in the inflammatory response and frameshifts are often found in endometrial and lung cancers." (PMID 25929336, 2015). "Likewise, phospholipase C gamma 1 (PLCG1) and caspase 5/8 (CASP5/8) also exert antitumor effects in cancer." (PMID 35923703, 2022). "Interestingly, except AIM2 was negatively associated with DLBC and CASP5 was negatively associated with COAD and READ in ESTIMATE score and stromal score, others were positively associated with cancers in the immune score, stromal score, and ESTIMATE score." (PMID 34906145, 2021). "Specifically, CASP5 may play different roles in various cancers." (PMID 35255915, 2022). "The “Target” run with ANGPTL3 as a target gene shows that altered genes of various cancer types including MAPK1, CASP5, COL3A1, ITGAM and TMEM59L change the expression of ANGPTL3." (PMID 37375208, 2023). "GSDMC, NLRP7, CASP5, PYCARD, IL18, IL1B and GSDMA were significantly upregulated in 22, 18, 18, 18, 18, 16 and 17 types of cancers, respectively." (PMID 35246158, 2022). "CTSG, NLRP9, DFNB59, APIP, SCAF11, CASP5 and NAIP showed significant downregulation across cancers." (PMID 36605187, 2022). "No significant expression of CASP5 mRNA was detected in all human cancer cell lines examined (data not shown), and therefore we focused on CASP4 in this study." (PMID 33452234, 2021).